SEMA4D (semaphorin 4D)
Diseases named in the same sentence as SEMA4D in open-access papers (continued):
Sharing a sentence is not in itself a finding about the gene and the disease.
multiple sclerosis (12 papers, 2015 to 2025). A progressive autoimmune disorder affecting the central nervous system resulting in demyelination. "In a variety of diseases (Kawasaki disease, multiple sclerosis, and rheumatoid arthritis), the SEMA4D/CD72 axis leads to increased levels of cytokines and results in worse prognosis." (PMID 39329961, 2024). "In particular, SEMA4D was selected as a potential therapeutic target in Huntington disease (HD), multiple sclerosis (MS) and lastly AD." (PMID 37332353, 2023). "This method, used to examine the role of semaphorin 4D (SEMA4D) in an experimental autoimmune encephalomyelitis (EAE) model of multiple sclerosis (MS) has provided crucial insights into the role of inflammation in neurodegeneration which are relevant to AD pathology as well." (PMID 39692624, 2025). "The inhibition of SEMA4D/PlexinB1 signaling has been found to show clear therapeutic effects in multiple types of tumors, rheumatoid arthritis, multiple sclerosis, Huntington's disease, and stroke in preclinical studies." (PMID 31943789, 2020). "Secreted semaphorins could be drug targets for neurodegenerative diseases; for instance, Sema4D antibody was used to rescue cognitive dysfunctions in a mouse model of Huntington disease, and depletion of Sema7A has been suggested as a possible treatment for multiple sclerosis." (PMID 37316917, 2023). "As a result of its role in the regulation, activation and migration of inflammatory cells, Sema4D is the target of a therapeutic antibody (VX15/2503, Vaccinex Inc.)currently in phase I clinical trials for patients with multiple sclerosis (ClinicalTrials.gov identifier: NCT01764737)." (PMID 25624520, 2015). "This receptor is also involved in the Sema4B-mediated inflammation in microglia/macrophages, the Sema4D-mediated cartilage destruction, the Sema4A-induced secretion of IL-17 by CD4+ T cells of systemic sclerosis patients and the Sema4D-mediated inflammation in a mouse model of multiple sclerosis." (PMID 40598553, 2025).
colorectal cancer (11 papers, 2016 to 2025). A primary or metastatic malignant neoplasm that affects the colon or rectum. "SEMA4D was identified through association of its alternative splicing with colorectal cancer risk, highlighting the importance of studying this mechanism using TWAS approaches." (PMID 40447568, 2025). "Contrary to the predictions obtained from GEPIA, SEMA4D was found to be upregulated highly in colorectal cancer and in several other types." (PMID 38544823, 2024). "Our previous study described the presence of gradient changes in SEMA4D expression in infiltrating immune cells at the tumor edge in human colorectal cancer." (PMID 37287907, 2023). "The immunohistochemical staining of colorectal cancer tissue specimens revealed that 95 (42 %) and 105 (46.4 %) of the specimens were positive for Sema4D and Plexin B1, respectively." (PMID 27456345, 2016). "The immunohistochemical staining of colorectal cancer tissue specimens revealed that 95 (42 %) and 105 (46.4 %) of the specimens were positive for Sema4D and PlexinB1." (PMID 27456345, 2016). "The likely causal genes included a previously unreported colorectal cancer susceptibility gene, SEMA4D, neither located at known colorectal cancer GWAS risk loci nor previously identified by colorectal cancer TWAS." (PMID 40447568, 2025). "In this study, we aimed to evaluate the expression of SEMA7A, SEMA4D, ADAM8, and ADAMTS10 in colorectal cancer (CRC) in relation to the mutational landscape of KRAS, NRAS, BRAF, PIK3CA, and AKT genes, microsatellite instability (MSI) status, and clinicopathological features." (PMID 39329961, 2024). "Additionally, in vivo tumor angiogenic assay also showed that SEMA4D induces an angiogenic response, thereby promoting colorectal cancer growth in a mouse model." (PMID 37504226, 2023). "Semaphorin 4D (SEMA4D), a protein originally demonstrated to regulate the immune system and axonal growth cone collapse in the developing central nervous system, is overexpressed in various human malignancies, including colorectal cancer (CRC)." (PMID 34337054, 2021). "Binding to Sema4D and PlexinB1 induce angiogenesis and invasive growth in colorectal cancer (CRC)." (PMID 27456345, 2016). "However, the correlation between the expression of Sema4D and PlexinB1 and the relapse-free survival in patients with colorectal cancer remains controversial." (PMID 27456345, 2016). "Immunohistochemical analysis evidenced the expression of both Sema4D and HIF-1α in about 60% of colorectal carcinoma tissue and in about 10% of normal mucosa." (PMID 33858502, 2021).
osteoporosis (11 papers, 2016 to 2023). A condition of reduced bone mass, with decreased cortical thickness and a decrease in the number and size of the trabeculae of cancellous bone (but normal chemical composition), resulting in increased fracture incidence. "Leptin or melatonin improved Sema4d's role in trabecular bone microstructure, bone production, and repairment of trabecular bone loss in osteoporosis rats." (PMID 37031174, 2023). "In conclusion, leptin and melatonin reversed the activation of osteoclasts caused by overexpression of Sema4D, which intensified the pathological process of osteoporosis." (PMID 37031174, 2023). "And serum Sema4D is reported to be increased in postmenopausal osteoporosis patients and has an inverse association with lumbar spine bone mineral density, bone alkaline phosphatase, and bone Gla-protein levels." (PMID 32382577, 2020). "Together with our experimental findings, we found that overexpression of Sema4D can exacerbate osteoporosis damage; therefore, we conclude that Sema4D regulates the differentiation of osteoblasts in osteoporosis and is one of the major factors that cause osteoporosis." (PMID 37031174, 2023). "Administration of an anti-SEMA4D antibody prevents bone loss in a mouse model of postmenopausal osteoporosis and promotes bone formation without affecting osteoclast-mediated bone resorption, suggesting that SEMA4D is a potential therapeutic target for osteoporosis or other low bone mass disorders." (PMID 32927921, 2020). "Sema4D has been discovered to be expressed on osteoclasts in recent years, inhibiting bone production and possibly contributing to the onset of osteoporosis and osteosclerosis." (PMID 37031174, 2023). "In brief, Sema4D-knockout mice showed an increase in bone thickness and density in a mouse model of osteoporosis, and Sema4D expressed on osteoclasts suppresses osteoblast differentiation via receptor PlexinB1." (PMID 35628440, 2022). "Sema4D (semaphorin 4D) is involved in the immune system and related to bone injury, osteoporosis, osteoblast differentiation, and rheumatoid arthritis." (PMID 32382577, 2020). "In contrast, anti‐Sema4D‐mAb could regain lost bone contents in osteoporosis‐induced ovariectomized mice, suggesting the translational value of targeting Sema4D in bone lytic disorders." (PMID 37170687, 2023). "Using an OVX rat model, the current work intends to investigate the effects and processes of Sema4D, Sema4D paired with leptin, and Sema4D combined with melatonin on bone metabolism in an effort to identify possible molecular targets for osteoporosis therapeutic treatment." (PMID 37031174, 2023). "Furthermore, it is reported that the serum Sema4D level in rheumatoid arthritis and postmenopausal osteoporosis patients was higher than that in healthy subjects." (PMID 35628440, 2022). "In summary, we here describe the generation and characterization of an anti–Plexin-B1 antibody that specifically interferes with binding of Plexin-B1 to its high-affinity ligand, Sema4D, and validate its therapeutic efficacy in preclinical mouse models of osteoporosis and MS." (PMID 35850304, 2022). "In postmenopausal women, serum Sema4D was higher among those with osteoporosis." (PMID 29971044, 2018). "Given the pathophysiological importance of the Sema4D–Plexin-B1 interaction in mouse models of osteoporosis and MS, a pharmacological intervention to block their interaction could represent a promising therapeutic approach to treat osteoporosis and MS." (PMID 35850304, 2022). "Sema4D-/- mice demonstrate a mild osteosclerotic phenotype, identical to Plexin-B1−/− mice and mice expressing dominant-negative RhoA, so this signaling pathway could have therapeutic implications in diseases such as osteoporosis." (PMID 26910109, 2016). "Indeed, Sema4D knockout mice exhibit an osteosclerotic phenotype, so this signaling pathway may represent a potential target in the treatment of osteoporosis." (PMID 26910109, 2016).
osteoporosis (continued). "As genetic deletion of Sema4D or Plexin-B1 results in elevated bone mass in mice by promoting osteoblastic bone formation without affecting osteoclastic bone resorption, pharmacological inhibition of Plexin-B1 could potentially add a new anabolic principle to osteoporosis treatment." (PMID 35850304, 2022). "Injection of a SEMA4D-specific antibody markedly prevented bone loss in a postmenopausal osteoporosis model by promoting bone formation without affecting bone resorption, suggesting SEMA4D could be a new and potentially effective target for bone-increasing drugs." (PMID 29844945, 2018). "In the present study, the number of osteoclasts was significantly reduced after leptin overexpression in Sema4D-overexpressed OVX rats, which further verified that the improvement effect of leptin on osteoporosis might be related to the inhibition of osteoclast activation." (PMID 37031174, 2023). "There was no attempt to correlate the Sema4D levels with degree of osteoporosis, and serum Sema4D was assayed at only one time point, not allowing a determination of kinetics, which may differ among treatment groups." (PMID 29971044, 2018).
rheumatoid arthritis (11 papers, 2018 to 2025). A chronic, systemic autoimmune disorder characterized by inflammation in the synovial membranes and articular surfaces. "Sema4D has been shown to be implicated in the development of rheumatoid arthritis." (PMID 33013906, 2020). "The aim of this study was to evaluate the serum levels of Sema3A and Sema4D and to investigate their clinical significance in rheumatoid arthritis (RA)." (PMID 30538782, 2018). "Clinical studies in patients with rheumatoid arthritis (RA) have also demonstrated the importance of Sema4D-mediated pathways in disease pathogenesis, even when Ag is not clearly defined." (PMID 30134791, 2018). "Previous studies have shown that the eosinophils could constitutively express Sema4D, the expression of which increased in autoimmune diseases such as rheumatoid arthritis, systemic sclerosis as well as eosinophilic rhinosinusitis." (PMID 38111650, 2023). "Circulating Sema4D was increased in rheumatoid arthritis patients, which could serve as a marker for predicting radiographic progression in patients with rheumatoid arthritis." (PMID 32382577, 2020). "The finding that the autoimmune collagenous disease, Rheumatoid arthritis, and the Asthma patients with allergic inflammatory profile, showed comparable levels of Sema4D in plasma as HNSCC patients, suggests that Sema4D levels are associated with inflammation, rather than being specific to HNSCC." (PMID 29541402, 2018). "In rheumatoid arthritis (RA), Sema4D was elevated in both serum and synovial fluid from RA patients, and disease activity markers were correlated with serum Sema4D levels." (PMID 29971044, 2018). "In contrast, the elevated levels of soluble Sema4D protein in rheumatoid arthritis are not due to increased Sema4D mRNA expression but are driven by a disintegrin and metalloproteinase with thrombospondin motif 4 (ADAMTS4)-mediated proteolytic cleavage of membrane-bound Sema4D." (PMID 40507881, 2025). "Thus, it is theorized that the identification of a soluble form of Sema4D detected in the GCF of patients with PD, as well as serum Sema4D found in rheumatoid arthritis and postmenopausal osteoporosis, results from cleaving of membrane-bound Sema4D expressed on the cell surface." (PMID 35628440, 2022).
atherosclerosis (9 papers, 2013 to 2025). A disease characterized by the build-up of fatty material and calcium deposition in the arterial wall resulting in partial or complete occlusion of the arterial lumen. "Our previous study also showed that loss of Sema4d in apolipoprotein-E (ApoE)-deficient mice retards the progression of atherosclerosis." (PMID 35045890, 2022). "Sema4D is a type I integral membrane glycoprotein expressed by most hematopoietic cells that participate in the pathogenesis of atherosclerosis, which has been identified as an independent risk factor for CHD." (PMID 33632238, 2021). "Further examination of the Sema4D/PlexinB1 pathway may provide new ideas for the diagnosis and treatment of cardiovascular events caused by atherosclerosis and improve patient prognosis." (PMID 37138227, 2023). "Sema4D is expressed in human atherosclerosis, more specifically by plaque macrophages and foam cells." (PMID 37138227, 2023). "Sema4D is the first semaphorin family member that was shown to participate in the development of atherosclerosis." (PMID 30405423, 2018). "Like Sema4A, Sema4D, Sema3A, and Sema7A, reported to participate in atherosclerosis, are also widely investigated in immune cells." (PMID 30405423, 2018). "They concluded that Sema4D plays an integral role in the development of atherosclerosis by promoting neovascularization of the intima, facilitating macrophage infiltration in atherosclerotic plaques." (PMID 30405423, 2018). "Although Sema4D (also called CD100) is expressed in platelets, monocytes, macrophages and T cells, cell types that are pivotal in atherosclerosis, only a few studies have explored the roles of this semaphorin in the disease." (PMID 30324109, 2018). "Deletion of Sema4D in mice protects against atherosclerosis by attenuating platelet hyperactivity in the setting of hyperlipidemia or by reducing intimal neovascularization." (PMID 23741311, 2013). "This study examined whether semaphorin 4D (Sema4D), a class IV semaphorin involved in atherosclerosis development, is secreted by M1 macrophages and contributes to the calcification of vascular smooth muscle cells (VSMCs)." (PMID 40507881, 2025). "Through these interactions, Sema4D mediates both localized and systemic signaling cascades that regulate critical physiological and pathological processes, including immune modulation, angiogenesis, tumor progression, and atherosclerosis." (PMID 40507881, 2025). "Meanwhile, inflammatory stimulation may induce platelet Sema4D activation, enhancing leukocyte adhesion and transmigration into the subendothelium to accelerate the development of atherosclerosis." (PMID 30405423, 2018). "A few studies have been performed to establish a possible role for CD100 in the development of atherosclerosis in the mice model; they have shown that lack of Sema4D reduces platelet hyperactivity otherwise found in dyslipidemia, thus conferring protection against atherosclerosis." (PMID 24098722, 2013). "In addition, Sema4D may exacerbate vascular complications in DM patients by interacting with endothelial cells to promote vascular inflammation, endothelial dysfunction, microthrombus formation and atherosclerosis." (PMID 23741311, 2013).
colitis (9 papers, 2014 to 2024). Inflammation of the colon. "This is consistent with findings in murine models of colitis where decreased expression of SEMA4D significantly aggravated the disease with increased colonic ulceration and mucosal inflammatory cell infiltration." (PMID 39596507, 2024).
colon cancer (9 papers, 2012 to 2025). "Pepinemab (an anti-SEMA4D antibody) has achieved considerable antitumor therapeutic effects on resectable pancreatic and colon cancer." (PMID 37287907, 2023). "It has been reported that lymphocytes infiltrated in the tumor stroma of pancreatic and colon cancer are responsible for SEMA4D expression." (PMID 34337054, 2021). "Moreover, in a preclinical mouse colon cancer model, antibody blockade of SEMA4D has been shown to enhance the infiltration of immune cells into tumours, thereby promoting anti-tumour immune responses." (PMID 40447568, 2025). "Moreover, dihydromyricetin (DMY) exerted its antitumor effects through induction of the oxidative stress and inflammation in colon cancer cells following regulation of the SEMA4D expression." (PMID 34337054, 2021). "In this study, we could not clearly elucidate the cell in which Sema4D is expressed, although, we consider that Sema4D is also expressed in the T cells and B cells in the tumor stroma of colon cancer." (PMID 27456345, 2016). "The expression of Sema4D and PlexinB1 were analyzed by immunohistochemistry in tissue of stage I, II, and III colon cancers." (PMID 27456345, 2016). "Indeed, overexpression of Sema4D (along with Plexin-B1) is correlated with histological tumor type, TNM stage, and metastasis in prostate and colon cancers and a worse prognosis in both soft tissue sarcomas and osteosarcoma." (PMID 26910109, 2016).
Huntington disease (9 papers, 2020 to 2025). Huntington disease (HD) is a rare neurodegenerative disorder of the central nervous system characterized by unwanted choreatic movements, behavioral and psychiatric disturbances and dementia. "Similarly, elevated expression of Sema4D in neurons has been reported in association with Alzheimer’s and Huntington’s disease, where it appears to promote astrocyte reactivity." (PMID 39152101, 2024). "Immunotherapies, including scFvs, are available for a diversity of neurological disorder targets such as semaphorin 4D (Huntington’s disease); nerve growth factor; tau; α-synuclein; and amyloid β (Alzheimer’s disease, ALS, Parkinson’s disease)." (PMID 40643474, 2025). "In addition, pepinemab, a humanised anti-SEMA4D monoclonal antibody, has been evaluated in several clinical trials, including a Phase I trial in patients with multiple sclerosis (NCT01764737) and a Phase II trial in Huntington’s disease (NCT02481674)." (PMID 34502373, 2021).
osteosarcoma (9 papers, 2016 to 2024). A usually aggressive malignant bone-forming mesenchymal neoplasm, predominantly affecting adolescents and young adults. "Sema4D and plexin-B1 is associated with osteosarcoma, in which PYK2-PI3K-Akt pathway is activated to promote tumor progression." (PMID 37096066, 2023). "Several candidate osteosarcoma oncogenes found in a transposon-based forward genetic screen in mice are also hypomethylated and overexpressed in human osteosarcoma compared to normal osteoblasts, including SEMA4D, RAF1 and PAK1." (PMID 29056713, 2016). "Several oncogenes, including SEMA4D and SEMA6D, have been involved in axon guidance in human osteosarcomas." (PMID 36408691, 2023). "We also found that SEMA4D expression levels were inversely correlated to those of SCUBE3 in both GCTs and osteosarcoma samples from patients: higher levels of SEMA4D were found in osteoclast-rich samples in which SCUBE3 was low." (PMID 36138226, 2022).
lung cancer (8 papers, 2012 to 2024). A malignant neoplasm involving the lung. "SEMA4D binds to CD72 to promote the activity of CD8+ T‐cells in non‐small cell lung cancer patients." (PMID 37701532, 2023). "Later, SEMA4D secreted from a human lung cancer cell line were shown to inhibit osteoblast differentiation in vitro." (PMID 35775083, 2022). "Induction of Sema4D by hypoxia through a HIF-1α-dependent mechanism has been also evidenced in lung cancer, and up-regulation of a disintegrin and ADAM17 expressions by hypoxia has been identified as the cause of Sema4D induction." (PMID 33858502, 2021). "Moreover, SEMA4D expression was shown to contribute to the development of bone metastases in lung cancer, with its inhibition preventing the growth of various cancers in vivo." (PMID 39443302, 2024).